FBN1 (fibrillin 1)
Diseases named in the same sentence as FBN1 in open-access papers (continued):
Sharing a sentence is not in itself a finding about the gene and the disease.
Marfan syndrome (continued). "On note, FBN1 gene was included in the panel and was normal, furtherly disproving the initial suspect of Marfan syndrome." (PMID 34318601, 2021). "CEL can be an isolated ocular disease known as ectopia lentis syndrome (ELS) or be secondary to systematic disorders, such as Marfan syndrome (MFS), and both pathologies can be caused by fibrillin-1 (FBN1) mutations." (PMID 35237611, 2021). "Marfan syndrome (MFS, [OMIM #154700]) is caused by heterozygous variants in FBN1, which alter the function of the encoded fibrillin 1 protein, a component of the extracellular microfibrils." (PMID 33414558, 2021). "Marfan syndrome (MS) is a relatively common (3:5000) dominantly inherited disorder of connective tissue, caused by mutation of FBN1, encoding the gene for fibrillin-1, with variable clinical features in the musculoskeletal, cardiovascular and ocular systems." (PMID 35026102, 2021). "Marfan syndrome (MFS) is a genetic disorder of the connective tissue, mostly occurring due to a mutation in the fibrillin-1 gene, and affects 1/5,000 to 1/10,000 individuals." (PMID 34744997, 2021). "Marfan syndrome is an autosomal dominant disorder caused by a mutation in FBN1, which encodes fibrillin-1, a component of elastin-associated microfibrils, resulting in defective elastic fiber formation in the vascular wall." (PMID 35008739, 2021). "Changes in fibrillin-1 disturb elastic fibers’ integrity within the endothelial layer, leading to impaired endothelial permeability observed in patients with Marfan’s syndrome." (PMID 34572356, 2021). "Marfan syndrome (MFS) is a genetically determined systemic connective tissue disorder, caused by a mutation in the FBN1 gene." (PMID 34059089, 2021). "Marfan syndrome (MFS, OMIM 154700) is a connective tissue disease that is caused by mutations in fibrillin-1; it mainly affects several systems including cardiovascular, ocular, and musculoskeletal systems." (PMID 34957211, 2021). "Thoracic aortic aneurysms are frequently found in patients with rare genetic diseases, such as Marfan syndrome (fibrillin-1 defect), Ehlers-Danlos syndrome, and Loeys-Dietz syndrome." (PMID 32968712, 2020). "Marfan syndrome (MFS) is a rare hereditary connective tissue disorder (HCTD), caused by mutations in fibrillin-1 (FBN1) (OMIM 134797)." (PMID 33256748, 2020). "Marfan syndrome (MFS) is an autosomal dominant disorder of connective tissues, which is primarily associated with the mutation of FBN-1 gene on chromosome 15q21 encoding fibrillin-1, an essential glycoprotein in the extracellular matrix." (PMID 32972445, 2020). "In this study, we investigated the correlations between the FBN1 genotype–phenotype and aortic events (aortic dissection and aortic aneurysm) in patients with Marfan syndrome." (PMID 31830381, 2020). "These include Marfan syndrome (MFS), a connective tissue disease that is caused by mutations in the fibrillin-1 (FBN1) gene." (PMID 33182307, 2020). "Marfan syndrome (MFS) is a connective tissue disease caused by variants in the FBN1 gene." (PMID 32514132, 2020). "In the nonseizure group, the yield was 44% (4/9), including one with SCN2A with autism, one FBN1 with Marfan syndrome, one DMD with muscle dystrophy, and one SPTBN2 with spinocerebellar ataxia." (PMID 33333793, 2020). "FBN1 is one of candidate genes for MMVD predisposition, because it regulates TGF-β signaling and is associated with Marfan syndrome, which represents one of the syndromic forms of human mitral valve prolapse." (PMID 33081147, 2020). "Both RNA-seq and RT-qPCR results showed highest expression of FBN1 in the cardiac valves, particularly the aortic valve, consistent with the valve failure seen in patients with Marfan syndrome." (PMID 33101359, 2020).
Marfan syndrome (continued). "In Marfan syndrome, the dysfunction of FBN1 leads to aortic aneurysms and elastic fiber calcification." (PMID 33101359, 2020). "Marfan syndrome (MFS) is a dominant monogenic disease caused by mutations in fibrillin 1 (FBN1)." (PMID 33200202, 2020). "Marfan syndrome (MFS) is a dominant monogenic disorder caused by mutations in fibrillin 1 (FBN1)." (PMID 31950671, 2020). "Using ZFNs and somatic cell nuclear transfer (SCNT) technologies, Umeyama and colleagues (2016) generated a heterozygous fibrillin-1 (FBN-1) mutant pig model of Marfan syndrome." (PMID 31979133, 2020). "The importance of fibrillin-1 in the function of tissues is further highlighted by fibrillin-1 mutations that cause a number of heritable connective tissue disorders termed fibrillinopathies, such as Marfan syndrome (MFS), Weill Marchesani syndrome (WMS) and geleophysic dysplasia (GD)." (PMID 30016650, 2019). "Mutations in FBN1 result in Marfan syndrome (MFS) but domain‐specific FBN1 mutations have been found in other connective tissue disorders including Weill‐Marchesani syndrome, stiff skin syndrome, isolated ectopia lentis, and acromicric dysplasia, in addition to GPHYSD." (PMID 31350823, 2019). "Genetic causes that have been associated with intracranial aneurysms are polycystic kidney disease and potentially Marfan syndrome with the fibrillin-1 (FBN1) gene and Neurofibromatosis type 1." (PMID 31052208, 2019). "Marfan syndrome (MFS) is an inherited disorder that affects connective tissue, caused by mutations in FBN1, the gene encoding the ECM protein fibrillin-1." (PMID 31108916, 2019). "Marfan syndrome (MFS) is an autosomal dominant inherited disorder of the connective tissue, characterized by mutations in the Fibrillin-1 gene (FBN1)." (PMID 30841577, 2019). "Although glaucoma generally has been associated with Marfan syndrome, there currently exists insufficient evidence to associate PDS/PG directly with Marfan syndrome or variants in FBN1." (PMID 29780638, 2018). "The diagnosis of Marfan syndrome is based on family history, the presence of certain clinical features such as aortic root dilatation and ectopia lentis, and genetic testing for FBN1." (PMID 30151001, 2018). "Marfan syndrome (MFS) is an inherited autosomal dominant connective tissue disease, mostly related to mutations in the fibrillin-1 (FBN1) gene." (PMID 28302143, 2017). "The strength of the association between FBN1 variants and aortic disease in BAV is similar to that in Marfan syndrome." (PMID 28993736, 2017). "Some of the down-regulated genes identified in the DNA array analysis involve those responsible for hereditary connective tissue disorders, including collagens and ADAMTS2 for EDS and fibrillin-1 for Marfan syndrome." (PMID 28422173, 2017). "Marfan syndrome (MFS, OMIM #154700) is a heritable connective tissue disorder caused by mutations in the fibrillin-1 (FBN1) gene (OMIM 134797), which encodes a major component of extracellular microfibrils." (PMID 28708846, 2017). "The distinction between qualitative and quantitative FBN1 mutations is important as this drug decreases TGF-β1 production, offsetting the increased circulating levels of this growth factor seen in Marfan syndrome and BAV." (PMID 28993736, 2017). "Fibrillin-1 and -2 are the defective gene products in Marfan syndrome and congenital contractural arachnodactily, respectively." (PMID 28252045, 2017). "The aim of the current study was to elucidate their functional role using a mouse model for Marfan syndrome, defective in fibrillin-1, the major structural component of the microfibril bundles that constitute most of the elastic fibers." (PMID 28395026, 2017). "SGS shares with Marfan syndrome, as it is also caused by mutation in the Fibrillin-1 gene (FBN1) located on 15q21.1, the same gene responsible for Marfan syndrome." (PMID 27761171, 2016).
Marfan syndrome (continued). "This article contains data related to the research article entitled “Expression of FBN1 during adipogenesis: relevance to the lipodystrophy phenotype in Marfan syndrome and related conditions”." (PMID 27508231, 2016). "In patients with Marfan syndrome, defects in FBN1 lead to excess TGFβ signaling, which results in the pleiotropic manifestations of disease." (PMID 25917920, 2015). "Marfan syndrome is an autosomal dominant disease of the connective tissues, resulting from inherited dysfunction of the glycoprotein fibrillin-1 gene on chromosome 15, affecting 1 in 10,000 people." (PMID 25949273, 2015). "Marfan syndrome is a systemic connective tissue disorder caused by mutations in FBN1, the gene encoding extracellular matrix protein fibrillin-1." (PMID 26506064, 2015). "A high index of suspicion is needed, and for subjects suspected to have Marfan syndrome based on clinical grounds FBN1 testing should be considered." (PMID 26444669, 2015). "Three new variants, including 1 deletion in DSC2, 1 missense SNPs in LRP1, and 1 nonsense SNP in FBN1 were confirmed to exist only in Marfan syndrome patients." (PMID 24484584, 2014). "Patients with heritable connective disorders, such as Marfan syndrome patients with a defect of the glycoprotein fibrillin-1, and Ehlers-Danlos syndrome patients with a type III-procollagen disorder are known to develop aortic dissection." (PMID 24586754, 2014). "Marfan syndrome (MFS): MFS is a life-threatening, autosomal dominant disease with mutations identified in FIBRILLIN-1 (FBN1)." (PMID 25621177, 2014). "Marfan’s syndrome is a disorder of connective tissue caused by mutations in the FBN1 gene, which encodes fibrillin-1." (PMID 23531534, 2013). "Mutations in fibrillin-1 (FBN1) cause a wide spectrum of disorders, including Marfan syndrome, which have in common defects in fibrillin-1 microfibrils." (PMID 23444230, 2013). "Haploinsufficiency for FBN1 appears to be the mechanism responsible for the majority of cases of Marfan syndrome." (PMID 24348270, 2013). "Cardiovascular complications are the leading cause of mortality and morbidity in Marfan syndrome (MFS), a dominantly inherited disorder caused by mutations in the gene that encodes fibrillin-1." (PMID 24289736, 2013). "Marfan syndrome is an autosomal-dominantly inherited disease of the connective tissue that is caused by mutations of the fibrillin-1 (FBN1) gene, which encodes fibrillin-1 monomers of the extracellular microfibrils." (PMID 24349050, 2013). "The study suggested that common genetic variants at 15q 21.1, (that probably act via FBN1) are associated with sporadic TAAD, suggesting a common pathogenesis of aortic disease in Marfan syndrome and sporadic TAAD." (PMID 23450299, 2012). "The EXT1 and EXT2 genes (30 cases) for multiple cartilaginous exostoses, the FBN1 gene for Marfan syndrome (24 cases), and the FGFR3 gene for achondroplasia (22 cases) were most frequently reported in Chinese biomedical literature from the CBM database." (PMID 22913777, 2012). "Marfan syndrome (MFS) which is a connective tissue disorder with multisystemic manifestations involving skeletal, cardiovascular and ocular systems caused by mutations in a very large gene FBN1." (PMID 22436252, 2012). "Mutations in fibrillin-1 cause the pleiotropic features of the Marfan syndrome (MFS, OMIM#154700)." (PMID 22242013, 2012). "One of the most common of these syndromes is Marfan syndrome (MFS), resulting from a mutation in the FBN1 gene which encodes the ECM glycoprotein fibrillin-1." (PMID 21858106, 2011). "The most common familial TAA is Marfan syndrome (MFS), which is primarily caused by mutations in fibrillin-1 (FBN1) gene." (PMID 20937124, 2010). "There are several other genetic conditions that exhibit abnormal CCT measurements, including Marfan syndrome and aniridia, thus implicating the defective genes, fibrillin-1 (FBN1) and paired box 6 (PAX6), respectively, as potential modifiers of CCT." (PMID 20360993, 2010).
Marfan syndrome (continued). "The results from skin biopsies of 3 family members with TAAD were reported as suggestive for Marfan syndrome based on abnormal expression of FBN1 in fibroblasts." (PMID 20937124, 2010). "On the one hand, mutations that affect the structure or expression of fibrillin-1 perturb microfibril biogenesis, stimulate improper latent TGF-β activation, and give rise to the pleiotropic manifestations in Marfan syndrome (MFS)." (PMID 21126338, 2010). "Marfan's syndrome and congenital contractural arachnodactyly (CCA) result from dominant mutations in the genes FBN1 and FBN2 respectively." (PMID 20161761, 2010). "Two such connective tissue disorders are Marfan's syndrome and Congenital Contractural Arachnodactyly (CCA), which are caused by dominant mutations in the fibrillin-1 (FBN1) and fibrillin-2 (FBN2) genes respectively." (PMID 20161761, 2010). "The most usual etiologic factor of aortic dissection in young patients in Marfan syndrome, related with defective fibrillin 1 synthesis." (PMID 20181187, 2009). "While FBN1 is a well-established gene for Marfan syndrome, COL5A1, primarily associated with Ehlers-Danlos syndrome (EDS), has been reported in cases where EDS and Marfan syndrome are difficult to distinguish due to overlapping connective tissue abnormalities." (PMID 41411243, 2025). "While the idea that abnormally activated TGFβ signaling is responsible for Marfan syndrome and related disorders remains uncertain, it is evident that FBN1 and components of the TGFβ signaling pathway, including TGFβR1 and TGFβR2, share overlapping genetic mechanisms." (PMID 40243722, 2025). "The mgΔloxPneo (Fbn1 mgΔlpn mice) mouse is a dominant-negative model for Marfan syndrome." (PMID 40695874, 2025). "Another disorder that can lead to concurrent skeletal and aortic abnormalities is Marfan syndrome (MFS), a heritable connective tissue disease caused by mutations in the fibrillin-1 (FBN1) gene, which plays a key role in microfibril and elastic fiber formation." (PMID 41394904, 2025). "The Fibrillin-1 gene (FBN1) encodes a crucial extracellular matrix protein that is widely distributed in connective tissues and plays a significant role in the pathogenesis of Marfan syndrome." (PMID 40129967, 2025). "Notably, the phenotype pattern of FBN1 rare LoF carriers was weaker than that of diagnosed Marfan syndrome patients, as reflected by lower intra-group similarity scores." (PMID 41411243, 2025). "For instance, Autosomal Dominant Polycystic Kidney Disease (ADPKD) is primarily attributed to pathogenic variants in the PKD1 and PKD2 genes, while Marfan syndrome and Neurofibromatosis type 1 (NF1) are mainly associated with the FBN1 and NF1 genes, respectively." (PMID 41411243, 2025). "This suggests that FBN1 exhibits incomplete penetrance for Marfan syndrome and that additional phenotype patterns may exist beyond those explained by FBN1 alone." (PMID 41411243, 2025). "In Marfan syndrome, this balance could be disrupted by perturbations in fibrillin-1 and other signaling cascades, such as TGF-β, and ends with disrupted bone formation, diminished BMD, and increased likelihood of fractures." (PMID 41541920, 2025). "Consequently, the quantity of functional Fibrillin-1 protein, determined by FBN1 expression levels, is closely linked to the onset and progression of Marfan syndrome." (PMID 40129967, 2025). "Individuals with Marfan syndrome have a defect in the FBN1 gene, which produces fibrillin." (PMID 40809613, 2025). "The identification of fibrillin 1 gene pathogenic variants in BAV patients without Marfan syndrome is fully consistent with the present findings." (PMID 41475307, 2025). "Moreover, the use of pluripotent stem cells to model various embryonic origins of VSMCs has revealed an inherent upregulation of FBN1 expression in neural crest VSMCs that drives the incidence of ATAA in Marfan syndrome." (PMID 38700707, 2024).
Marfan syndrome (continued). "Interestingly FBN1, the predominate genetic source (including gene loci 15q21) of Marfan syndrome has been identified by multiple studies on separate populations as strongly associated SNPs with ATAA progression and development." (PMID 38700707, 2024). "As homocystinuria shares many features with Marfan syndrome, it has been hypothesised that raised homocysteine levels resulted in disruption to fibrillin-1 microfibrils." (PMID 39766898, 2024). "Marfan syndrome (MFS) is an autosomal dominant condition characterized by aortic aneurysm, skeletal abnormalities, and lens dislocation, and is caused by variants in the FBN1 gene." (PMID 37684520, 2024). "We selected FBN1-related Marfan syndrome (MIM: 154700) as an example." (PMID 38103548, 2024). "In addition to its role in Marfan syndrome, Fibrillin-1 has been found to be involved in the regulation of the TGF-β signaling pathway, which controls the dispersal, storage, and release of ligands." (PMID 37784117, 2023). "In addition, it was located in a highly conserved region of fibrillin-1, where other pathogenic genetic variants have been found in connection to TAAD and Marfan syndrome." (PMID 36346469, 2023). "Marfan syndrome (MFS), typically caused by mutations in the FBN1 gene encoding fibrillin-1, which plays important roles in systemic connective tissues and affects the integrity and function of extracellular matrix protein, is a multisystem inherited disorder of autosomal dominant inheritance." (PMID 36983580, 2023). "Thus, fibrillin-1 fragmentation in Marfan syndrome or alteration of the TGF-β binding domain in other fibrilinopathies can further exacerbate TGF-β signaling and create positive-feedback loops." (PMID 37001705, 2023). "These systemic syndromes can be caused by a series of genes, including NYX, CACNA1F, GRM6, and LRIT3, responsible for congenital stationary night blindness (CSNB); COL2A1, COL11A1, COL9A1, and COL9A2, responsible for Stickler syndrome; and FBN1, responsible for Marfan syndrome." (PMID 36980859, 2023). "FBN1 encodes fibrin, an ECM glycoprotein, whose mutation was first identified in Marfan syndrome." (PMID 36737432, 2023). "Finally, we provided evidence that FBN1 is involved in normal IVD function by analyzing IVDs in patients with Marfan syndrome and suggested the potential role of ADAMTS17 in the AF of IVDs." (PMID 36966180, 2023). "It is hypothesized that this fragment degraded from FBN1 protein in pathological situations where there is increased proteolysis or inflammation might contribute to the phenotype in Marfan syndrome." (PMID 36176293, 2022). "Patients with Marfan syndrome (MFS) develop thoracic aortic aneurysms as the aorta presents excessive elastin breaks, fibrosis, and vascular smooth muscle cell (vSMC) death due to mutations in the FBN1 gene." (PMID 36577770, 2022). "One other individual with a FBN1 variant that did not meet pathogenicity criteria exhibited some traits like Marfan syndrome but not the trademark tall stature." (PMID 35918752, 2022). "This suggests that pathogenic variants in the FBN1 gene are not the only genetic factors contributing to expression of symptoms in Marfan syndrome." (PMID 35918752, 2022). "Apart from mutations in the fibrillin-1 gene, also changes within transforming growth factor β receptor 2 (TGF-βR2) and TGF-βR1, which regulate extracellular matrix synthesis and homeostasis, can cause Marfan’s syndrome." (PMID 34572356, 2021). "Although Marfan syndrome is well established as an inherited connective tissue disorder caused by mutations in the fibrillin-1 gene, the exact mechanism of pathogenesis has not been fully resolved." (PMID 33801742, 2021). "Marfan syndrome (MFS) is a common inherited connective tissue disorder, caused by FBN1 mutations." (PMID 33735269, 2021). "LVNC was associated with FBN1 mutation combined with DCM and Marfan syndrome." (PMID 34819141, 2021).